ENSG00000295151 (novel transcript)
Gene: Long non-coding RNA gene on chromosome 8 (54,152,522 to 54,208,172, forward strand). Ensembl gene ENSG00000295151.
Gene Ontology:
Molecular function: pre-mRNA 5'-splice site binding; U4atac snRNA binding
Biological process: mRNA 5'-splice site recognition; spliceosomal tri-snRNP complex assembly
Cellular component: U6atac snRNP